IL10 (interleukin 10)
Diseases named in the same sentence as IL10 in open-access papers (continued):
Sharing a sentence is not in itself a finding about the gene and the disease.
infection (continued). "During asymptomatic infection, IL-10 could act as a regulatory cytokine to maintain the balance Th1/ Th2 cytokines production and thus suppress inflammatory response and promote the preservation of parasites." (PMID 36787308, 2023). "Furthermore, infection increased the IL-10 concentration exclusively in intact females, resulting in a dimorphic pattern that was eliminated by DHEA administration." (PMID 37628731, 2023). "Low infection prevalence and intensities could also be the reason for low sensitivity of urinary IL-6 and IL-10 but further studies should shed more light on this." (PMID 37018184, 2023). "Moreover, opposed to WT mice, S100A9 KO mice showed substantially increased BAL fluid levels of pro-inflammatory TNF-α and IL-1β and anti-inflammatory IL-10 on day 2 post-infection." (PMID 37467233, 2023). "The infection with Mtb increased the production of IL-10, IL-13, and IL-5." (PMID 37375056, 2023). "Compared with those produced by E. coli DH5α-injected mice, E. coli JE5505-injected mice produced high levels of TNF-α, IL-1β, and RANTES and a low level of IL-10 in their livers, lungs, and sera after infection at indicated time points (3 h or 6 h postinfection; P < 0.05)." (PMID 36916913, 2023). "Bacterial burden was significantly reduced in IL-10 KO mice in the brain and galea at day 14 post-infection compared to WT animals, concomitant with increased CD4+ and γδ T cell recruitment and cytokine/chemokine production, indicative of a heightened proinflammatory response." (PMID 37179295, 2023). "Finally, we explored the possibility that IL-10 production by G-MDSCs was one mechanism responsible for S. aureus persistence during craniotomy infection, given that Mrp8CreIL-10 fl/fl mice had lower bacterial burden in the galea where G-MDSCs are abundant." (PMID 37179295, 2023). "Naïve MSCs significantly lowered the amount of IL-10 present which may be due to the resolution of the infection already occurring." (PMID 37259300, 2023). "However, we observed a peak in the frequency and number of IL-10-expressing MDSCs in the second week of infection." (PMID 36776848, 2023). "Given that DMI suppresses IL-6 and IL-10 and induces autophagy in macrophages during infection, we evaluated its effect on the activation of the transcription factor STAT3, which modulates gene expression in response to IL-6 and IL-10 and the suppression of autophagy." (PMID 36882813, 2023). "Furthermore, CP26 infection induced a higher (p < 0.05) expression of IL-10 compared to the control and CP5 groups." (PMID 36985344, 2023). "In addition, Karp infection induced higher IFN-γ, Eotaxin, IL-17, and IL-10 at days 8 or 12, indicating the stronger immune responses by Karp at late stages of infection." (PMID 38091346, 2023). "Furthermore, the MDSC transfer plus poly(I:C) administration group exhibited elevated levels of IL-10, an anti-inflammatory cytokine that plays a pivotal role in maintaining immune homeostasis by facilitating the clearance of infection." (PMID 37818369, 2023). "Compared to wildtype pups, TLR2-deficient pups inoculated with Group B Streptococcus at P2 were not susceptible to sepsis and did not produce increased amounts of IL-10 associated with damaging inflammation in wildtype pups at 24 h after infection (P3)." (PMID 37375099, 2023). "Furthermore, this study suggests that neutralizing both IL-27 and IL-10 better control M. tuberculosis, thus co-neutralization is of better therapeutic value during infection." (PMID 36863206, 2023). "However, when the infection occurs in pregnant women, there is an increase in the production of IL-10, IL-6, IL-17, TNF-a, IFN-a, and IFN-g." (PMID 37376620, 2023). "While IL-10 primarily protects the host against immune-mediated pathology by preventing excessive inflammation, it also restricts Th1 and Tfh cell responses, increasing the time needed to clear the infection and resulting in a higher parasite burden." (PMID 37843306, 2023).
infection (continued). "In addition, we have recently demonstrated an increased IL-10 production by BMDCs following LDAm infection." (PMID 37125906, 2023). "IL-10 production is stimulated after an infection to control the inflammatory response, but if a secondary infection begins after inflammatory responses have been halted, that secondary infection can become deadly." (PMID 38138118, 2023). "Finally, we discuss the role of B cells in mouse infection models where IL10, IgA, or IgG contribute to the outcome of the infection." (PMID 37849749, 2023). "Furthermore, infection with a virulent BoHV-1 isolate triggered increased serum levels of IL-10, which paralleled the peak of TNF." (PMID 37112697, 2023). "The M1-related cytokines, IFN-γ and TNF-α, increased and reached a peak at the 6th week post-infection (with IFN-γ higher than TNF-α), while the M2-related cytokines, IL-10 and IL-13, were boosted during the late stage of infection (with higher IL-10 than IL-13)." (PMID 36668953, 2023). "IL-10 plays an important role in wound healing as well as response to infections." (PMID 36978418, 2023). "Consequently, IL-10 can delay the time needed to resolve this infection, leading to a higher parasite burden." (PMID 37843306, 2023). "IL-10 production in DENV-infected individuals may be exacerbated by antibody-dependent enhancement of infection." (PMID 35631079, 2022). "The expression level of IFN‐γ, IL‐17, IL‐4, and IL‐10 increased with the duration of infection." (PMID 36169259, 2022). "Furthermore, levels of IFN-γ, IL-12 and IL-10 were also analysed during the infection in Balb/c mice to further re-confirm the results." (PMID 35109868, 2022). "Researchers observed that moMφ’s infection with virulent Georgia 2007 resulted in downregulated expression of anti-inflammatory IL-10 and upregulated expression of IL-17 and cytokines of TNF superfamily, including FASL, LTA, LTB, TNF, TNFSF4, TNFSF10, TNFSF13B, and TNFSF18." (PMID 35215216, 2022). "Together these findings may suggest that a triad MIF/GC/IL-10 can be operative during infections in the regulation of inflammation." (PMID 35464430, 2022). "Interestingly, IFN-γ/IL-10 ratio still remained higher than 1 and more profound than observed at 7 d post-infection." (PMID 36039381, 2022). "Treg IL-10 was upregulated during late infection, perhaps to combat the coincided inflammatory cytokines (IL-1, IL-18, and IL-6) high levels and intense pathological lesions, protect the host from excessive tissue damage, and contribute to the Th1/Th2 balance and immune homeostasis." (PMID 36187827, 2022). "Of the CD3+ cells, a higher percentage of CD4+ T cells, but not CD8+ T cells, from IL-10-deficient mice produced TGFβ1 at both 5 and 7 days after infection compared to WT mice." (PMID 36016413, 2022). "Therefore, microbiota-depleted IL-10−/− mice received synthetic DESF via the drinking water starting seven days before oral infection with C. jejuni strain 81-176." (PMID 36671455, 2022). "However, early in infection, the anti-inflammatory cytokines IL-10 and IL-22 were also locally and systemically upregulated in BaP-exposed S.E.-infected mice." (PMID 35203386, 2022). "Furthermore, IL-10, IL-12p70 and SDF-1α were found to be significantly associated with lower CD4:CD8 ratios during chronic phase (> 180 days post infection)." (PMID 35165387, 2022). "IL-10 is an anti-inflammatory cytokine and potent immunoregulator during infection." (PMID 35638785, 2022). "Moreover, the NE infection group showed lower mRNA expressions of ileal IL-4 and jejunal IL-10 compared to the TA administration group (P < 0.05)." (PMID 35387091, 2022). "The data from the present study suggest that IL-32γ in the heart lead to maintenance of IL-17 levels, producing an infection control and, together with IL-10, regulation of the immune response in order to avoid an intense inflammatory response and consequently cardiac damage." (PMID 35097133, 2022).
infection (continued). "For instance, interleukin 10 (IL-10) expression was increased in B cells upon infection, thus promoting a postulated polarization of macrophages to an immunosuppressive M2 phenotype, which was correlated to a known conducive environment for SIV transcriptional activation." (PMID 35447093, 2022). "The induction of IL-10 that we observed in the FV-Katushka-mTagBFP infected mice could be detected already in the early phase of infection and was as pronounced in SFFV single or F-MuLV/SFFV double-infected cells as in F-MuLV-infected cells." (PMID 36527061, 2022). "Hence, the observed enhancement of S.E.-antigen-induced IL-10 production of immune cells at the site of infection, as well as systemically in the spleen, through BaP was AhR-dependent." (PMID 35203386, 2022). "Additionally, ASFV-Δ9L/Δ7R infection exhibited dramatic induction of genes important during the acute-phase response, such as IL-1A, IL-1B, IL-10, and IL-18, tumor necrosis factor alpha (TNF-α), and several members of the complement pathway (C1R)." (PMID 35867564, 2022). "In this case, it would be advantageous since IL-10 could prevent or diminish some of the harmful effects of high levels of inflammatory cytokines such as IFN-γ yet help resolve the infection." (PMID 35154155, 2022). "Furthermore, using IL-10 reporter (Vert-X) mice, it has been found that NK cells, CD8+ and CD4+ T cells, B cells and plasma B cells represent potential cellular sources of IL-10 during the acute phase (first 10 days post-infection) of T. b." (PMID 35464430, 2022). "During extracellular pathogen infection, naïve Th cells proliferate and differentiate toward the Th2 subtype, which functions through secreting various effector cytokines, including IL-4, IL-5, IL-6, IL-10, IL-13." (PMID 35241075, 2022). "In the SILP, the percentage of CD8+ T cells, B cells and ILCs expressing IL-10 increased at day 7 (D7) post-infection with H. polygyrus compared to naïve controls, whereas the proportion of IL-10+ CD4+ T cells remained unchanged and there was a small decrease in IL-10+ myeloid cells." (PMID 35428872, 2022). "In summary, infection-induced Treg and Breg are often simultaneously useful in controlling inflammation, in large part through IL-10, but they may also have IL-10–independent functions and nonredundant roles." (PMID 35113966, 2022). "Similarly, E. coli 1587 infection stimulated upregulation of IL-1β, IL-6, IL-10, and TNF-α mRNA transcription levels in mouse colons at 3 dpi, but this phenomenon mostly diminished in 7 dpi except for IL-6." (PMID 35643532, 2022). "Furthermore, at the protein level, we also confirmed that all four Th2 cytokines (IL-4, IL-6, IL-10, and IL-13) were progressively enhanced in both mouse and rat lungs during the late infection phase of AC." (PMID 35617354, 2022). "Particularly, IL-6, IL-10, and IL-8 can serve as predictive markers of infection." (PMID 35463642, 2022). "Given the similarities in parapoxvirus pathology and the important virulence role that ORFV IL-10 plays during host infection, we hypothesised that the newly reported parapoxvirus IL-10s would exert similar biological effects to the ORFV IL-10." (PMID 35631028, 2022). "The presence of IL-10 from infected keratinocytes may contribute to an environment that favors infection by interfering with proper cellular immune response, although it can also contribute to containing the damage produced by hyperinflammation." (PMID 35628694, 2022). "In our study, the increased Foxp3 and IL-10 expression suggests that Treg proliferation could be favored after infection." (PMID 36544518, 2022). "IL-10 content was also higher in participants with P. falciparum single infection (224.5 [78.0–657.9] pg/mL) and in P. falciparum-filariae co-infected (18.1 [12.8–125.2] pg/mL) and STH- (39.5 [33.0–68.0] pg/mL) and intestinal protozoa-infected participants (26.9 [8.7–60.1] pg/mL)." (PMID 35421083, 2022).
infection (continued). "NK cells are required for acute T. gondii control, regulate infection via IL-10, and may contribute to adaptive immune responses." (PMID 36206304, 2022). "In L. infantum infection, the parasite benefits from the A2AR signaling pathway and promotes the development of an immunosuppressive response mediated by Tregs and IL-10; this inhibits specific Th1 responses, thus allowing the escape of parasites and establishment of infection." (PMID 35585983, 2022). "In contrast, the chronic stage of infection in trypanotolerant animals, so far only described for T. congolense infections, is hallmarked by the presence of a Th2 immune environment, with anti-inflammatory cytokines such as IL-10, IL-4, and TGFβ." (PMID 36420267, 2022). "Our previous study revealed that IL-10 antagonized the control of Mtb infection by promoting the generation of vasculature-associated CD4+ T cells with reduced ability to migrate into the lung parenchyma and induce control of infection." (PMID 35935958, 2022). "We, therefore, quantified SC mRNA levels encoding various pro-inflammatory and disease resolving factors, namely, the monocyte chemoattractant CCL2, TNF, IFNγ, a prominent mediator of MHV virus control, iNOS, IL10 and arginase 1 (Arg1) over the course of infection." (PMID 36333761, 2022). "Moreover, infants born to women with PM had lower levels of cytophilic IgG and higher levels of IL-10 during active infection." (PMID 35911674, 2022). "In contrast, only infection with B. canis induced significant production of IL-10 in the spleen." (PMID 36032120, 2022). "This single-centre observational clinical pilot-study intended to investigate the role of selective biomarkers for inflammation and infection (PCT, ferritin, uB2MG, IL-6, IL-8, IL-10 and TNF-α) following TTPB and their association with post-operative complications such as infection and bleeding." (PMID 36154663, 2022). "Il-6 and IL-10 can be used as indicators of anti-infection treatment effects." (PMID 35432366, 2022). "Thus, identifying the stage of infection in which patients are found can provide a better understanding of IL-10’s function." (PMID 36671466, 2022). "Administration of rWnt5A prior to infection was also found to correlate with slightly lower plasma levels of IL-4, which may act together with IL-10 to aggravate disease pathogenesis." (PMID 35197983, 2022). "In support of this hypothesis, recent evidence suggests a protective role of Tr1-like cells in murine gamma herpesvirus infection in which infection induced IL-10-producing monocytes within the lung that led to generation of Tr1-like cells." (PMID 36389662, 2022). "Therefore, there is a need for IL-10 to control a pathological immune response in the acute phase of infection." (PMID 35154155, 2022). "In our study there was an important increase in pro-inflammatory cytokines (IL1β, IL6, TNFα, IL18, IL23) upon infection in all the groups analyzed in comparison with age-related control samples, as also seen for the immunoregulatory cytokines IL10 and IL17A, and for Th1 IFNγ NLF." (PMID 36561744, 2022). "Additionally, while greater levels of IL-10 were also noted in previously infected mice following challenge compared to vaccinated mice, a significant drop in IL-10 was noted in the spleen between primary and secondary infection." (PMID 36032120, 2022). "IL-10 is a crucial mediator of the immune response to S. Typhimurium and previous data from our laboratory have described that IL-10 has a peak of expression at day 5 post-infection with S. Typhimurium present in the ileum, liver, and spleen of C57BL/6J mice." (PMID 35739937, 2022). "Similar observations were made at the level of DENV-specific CD4+ T cells, where the acute phase of infection was associated with a subset of CD4+ T cells that co-produced IL-10 and IFN-γ, but no altered phenotype was associated with DHFs." (PMID 35455361, 2022).
infection (continued). "In addition, it has been reported that, compared with 4 weeks post-infection, the level of IL-10 decreased significantly in 8 weeks post-infection in C57BL/6 mice spleen." (PMID 36310865, 2022). "Similarly, while holding day constant, infection status maintained a significant influence on Ifnγ, Il1β, Il10, and Cox2 abundance (p ≤ 0.0273), with tendencies for Tnf and Cox1 (p = 0.0569 and p = 0.0645, respectively)." (PMID 35312688, 2022). "In addition, the level and degree of expression of the genes investigated (e.g., IL-10) changed according to infection stage (3, 10, and 24 h after the addition of bacteria to the cell culture)." (PMID 35445115, 2022). "IL-10 is typically secreted from M2 macrophages and acts as an anti-inflammatory cytokine, restricting tissue damage during infection." (PMID 36093197, 2022). "Interestingly, IL-22, similar to IFN-λ, is another member of the IL-10 cytokine family that functions at epithelial mucosal barriers in response to infection." (PMID 36379255, 2022). "Because IL-10 has been suggested in the past to play a role in the immune response to FV infection, we were interested in the induction of this immunosuppressive cytokine and performed infection experiments in IL-10-eGFP reporter mice." (PMID 36527061, 2022). "IL-10 -/- homozygous mice showed greater lethality, from the third week post-infection, whereas the wild controls of this cytokine (IL-10 +/-) survived the acute infection." (PMID 35928208, 2022). "In our own experiments, by the analyses of cytokine genes in draining LN of C57BL/6 mice infected with different strains of L. major, we also noticed the higher expressions of both Ifng mRNA and Il12 mRNA and the lower levels of Il4 and Il10 expressions at five and eight weeks post infection." (PMID 35090305, 2022). "The proportion of IL-10+ cells that were CD8+ T cells also expanded in the SILP during infection." (PMID 35428872, 2022). "Specifically, while LmexWT inoculated hamsters developed a disease promoting cytokine response, as evident by the elevated IL-10 and IL-4 expression levels, LmexCen−/− immunized hamsters displayed a diminished expression of both these cytokines relative to LmexWT infection." (PMID 36463228, 2022). "In addition, the immunosuppressive cytokine IL-10 was also significantly down-regulated in KO rats, which displayed a notable significant difference at 7 weeks post-infection between both groups." (PMID 35584107, 2022). "In the early phase of infection, neutrophils were shown to be a dominant source of IL-10 and that increased levels of IL-10 might provoke the formation of different macrophage phenotypes." (PMID 36618344, 2022). "The elevated IL-10 expression in these hamsters might have played a role in reducing the immune cell infiltration to the site of infection (i.e., the lungs)." (PMID 35740365, 2022). "Indeed, infection of IL-10-/- mice with P. chabaudi chabaudi led to exacerbated pathology which was linked to increased expression of pro-inflammatory cytokines such as IFNγ, IL-12 and TNF." (PMID 35464430, 2022). "They showed, after M. tuberculosis infection, that IL-10 acts in late stages of the infection." (PMID 36678397, 2022). "Indeed, both naturally occurring CD4+ Foxp3+ Tregs as well as different myeloid cell subsets, including Ly6C- patrolling monocytes and alternatively activated macrophages, were shown to constitute sources of IL-10 during the early stages of infection." (PMID 35464430, 2022). "In collaboration with AMC Amsterdam, a cohort of seven D+R− kidney transplant patient samples from multiple timepoints post transplantation were analyzed using IFNγ and IL-10 FluoroSpots to establish when post-infection HCMV-specific T cells to a broad range of proteins develop." (PMID 36558866, 2022). "IL-10 plays a role in limiting the host immune response to pathogens and in maintaining tissue homeostasis by reducing the immunological response of the host to infection, thereby preventing damage to the host." (PMID 35638785, 2022).